PPARG (peroxisome proliferator activated receptor gamma)
Diseases named in the same sentence as PPARG in open-access papers (continued):
Sharing a sentence is not in itself a finding about the gene and the disease.
status epilepticus (6 papers, 2012 to 2020). Status epilepticus is defined as a continuous seizure lasting more than 30 min, or two or more seizures without full recovery of consciousness between any of them. "PPARγ activation has been previously found to be beneficial to epileptic neuronal injury as rosiglitazone reduced hippocampal neuronal loss in lithium-pilocarpine induced status epilepticus in rats." (PMID 26659605, 2015). "Our results showed a temporal decrease in PPARγ expression 6 h after experimental status epilepticus, followed by a significant increase of expression from 12 to 48 h in the hippocampal CA3 subfield." (PMID 22849356, 2012). "Therefore, the transient decrease of PPARγ expression in the hippocampus during experimental status epilepticus may be related to activation of NF-κB and other inflammatory responses." (PMID 22849356, 2012). "Oxidized protein level, translocation of Bcl-2, Bax and cytochrome c between cytosol and mitochondria, and expression of peroxisome proliferator-activated receptors γ (PPARγ) and UCP2 were examined in the hippocampal CA3 subfield following KA-induced status epilepticus." (PMID 22849356, 2012). "Expression of PPARγ and UCP2 increased 12–48 h after KA-induced status epilepticus." (PMID 22849356, 2012).
acute myeloid leukemia (5 papers, 2019 to 2024). Acute myeloid leukemia (AML) is a group of neoplasms arising from precursor cells committed to the myeloid cell-line differentiation. "They act via PPARγ to reduce the severity of acute myeloid leukemia (AML) in mouse models and patient cells, suggesting IL-4 as a potential additional therapeutic option for AML." (PMID 35954274, 2022). "Similarly, in acute myeloid leukemia (AML), the forced expression of PPARγ regulated the induction of apoptosis via caspase-8 activation." (PMID 35954274, 2022). "Given the promising results of pioglitazone in human leukemia, it was of particular interest to evaluate whether there is a difference in the expression level of PPARγ in acute myeloid leukemia (AML) patients and also to examine the therapeutic efficacy of pioglitazone in AML‐derived U937 cells." (PMID 34549887, 2021). "Preliminary results from our laboratory suggest that NHRs such as PPARG and RXRA were downregulated in chemoresistant acute myeloid leukemia (AML) cell lines, suggesting that NHRs can be modulated to improve chemosensitivity." (PMID 37324449, 2023). "We aimed to investigate the expression of PPARγ and one of its downstream targets PTEN in non‐M3 acute myeloid leukemia (AML) patients." (PMID 34549887, 2021).
adrenocortical cancer (5 papers, 2008 to 2021). "The impact of PPARγ activity on the adrenal gland has been evaluated in the context of an antitumor effect on adrenocortical cancer and altered adrenocortical steroidogenesis, specifically reduced aldosterone production." (PMID 31910209, 2020). "PPARγ is abundantly expressed in humanadrenal tumors including adrenocortical carcinomas and normal adrenal tissues.PPARγ agonists suppress adrenocortical tumorcell proliferation, increase apoptosis, and induce adrenal differentiation." (PMID 18584037, 2008).
age-related macular degeneration (5 papers, 2008 to 2019). Age-related loss of vision in the central portion of the retina (macula), secondary to retinal degeneration. "We postulated that DNA sequence variation in PPAR gamma (PPARG) co-activator 1 alpha (PPARGC1A), a gene encoding a co-activator of the LCPUFA-sensing PPARG-retinoid X receptor (RXR) transcription complex, may influence neovascularization (NV) in age-related macular degeneration (AMD)." (PMID 23335958, 2013).
alcoholic fatty liver disease (5 papers, 2020 to 2025). Lipid infiltration of the hepatic parenchymal cells that is due to alcohol abuse. "The PPARγ agonist rosiglitazone has been shown to exert anti-ferroptotic effects in non-alcoholic fatty liver disease models, suggesting that modulation of the PPARγ pathway may be a promising therapeutic strategy." (PMID 40563332, 2025). "Furthermore, butyrate exerts anti-inflammatory effects by upregulating the level of peroxisome proliferator-activated receptor gamma (PPARγ) and ameliorating alcoholic fatty liver disease." (PMID 37630721, 2023). "Although Pcal therapy elevated cardiac adiponectin levels in apolipoprotein-E deficient mice, it showed limited effects on hepatic adiponectin and leptin levels, as well as the expression of their receptors, PPARα, PPARγ, and SREBP-1 in rats with non-alcoholic fatty liver disease." (PMID 38139208, 2023). "Considering the already well-known alleviating bioactivity of A. cinnamomea for the alcoholic steatohepatitis (ASH), we propose that Ant can be beneficial to NAFLD, and that the AMPK/Sirt1/PPARγ/SREBP-1c pathways may be involved in such alleviations." (PMID 31935815, 2020).
benign prostatic hyperplasia (5 papers, 2005 to 2023). A non-cancerous nodular enlargement of the prostate gland. "Very weak immunohistochemical staining of PPARγ was shown in benign prostatic hyperplasia and normal prostate tissues, whereas significant enhancement in the expression of immunoreactive PPARγ was observed in malignant prostate tissues." (PMID 15583697, 2005). "Ke and colleagues found that the expression of both FABP5 and PPARγ, but not PPARβ/δ, increases in PCa cell lines compared to benign cell lines and prostatic hyperplasia tissues, and that the cytoplasmic levels of FABP5 correlate with nuclear immunointensity of PPARγ in PCa tissues." (PMID 33352874, 2020).
bladder urothelial carcinoma (5 papers, 2012 to 2025). "Conversely, in five types of cancer, such as pan-kidney cohort (KIPAN), kidney renal clear cell carcinoma (KIRC), bladder urothelial carcinoma (BLCA), READ, and uveal melanoma (UVM), low PPARG expression was associated with a poor prognosis." (PMID 38044948, 2023).
generalized lipodystrophy (5 papers, 2019 to 2024). Almost complete absence of subcutaneous and/or visceral adipose tissue. "According to the results of our literature search, except for 3 cases of generalized lipodystrophy, we retrieved cases concerned FPLD2 and FPLD3 related to LMNA or PPARγ mutation, respectively." (PMID 39479521, 2024).
glomerulonephritis (5 papers, 2008 to 2024). A renal disorder characterized by damage in the glomeruli. "In kidney, the deletion of PPARγ in hematopoietic cells enhances inflammatory renal disease in the anti-GBM antibody-induced glomerulonephritis mouse model." (PMID 32158560, 2020). "Mice lacking macrophage expression of PPARγ develop glomerulonephritis similar to autoimmune glomerulonephritis." (PMID 32158560, 2020).
hemorrhagic stroke (5 papers, 2014 to 2022). A stroke caused by a bleed on the brain. "PPARγ agonists, showing neuroprotective effects in an ischemic stroke, help in hemorrhagic stroke by hematoma absorption by 2.3-fold, resulting in decreased neuronal damage, and improved functional recovery." (PMID 33925299, 2021). "Activation of PPARγ mediated the conversion of microglia phenotype and phagocytic capabilities of peripheral M2 polarized macrophages in various CNS diseases, including hemorrhagic stroke." (PMID 35720361, 2022). "Furthermore, PPARγ agonists have been shown to suppress inflammation following ischemic and hemorrhagic stroke." (PMID 26659605, 2015). "PPARγ is induced during annexin 1-mediated microglial efferocytosis of apoptotic neurons, and also regulates CD36-mediated phagocytosis in the hemorrhagic stroke model." (PMID 33925299, 2021).
HIV-1 infection (5 papers, 2009 to 2017). The type species of lentivirus and the etiologic agent of acquired immunodeficiency syndrome (AIDS). "This review deals with the hypothesis that dysregulation of PPARγ may underpin the bone abnormalities associated with HIV-1 infection, and treats the current knowledge and prospective developments, in our understanding of PPARγ involvement in HIV-1-associated bone disease." (PMID 19325916, 2009). "For example, HIV-1 Nef has been found to be responsible for hematopoietic defects of the BM in HIV-1 infection, dependent on the presence and activation of the PPARγ signaling pathway." (PMID 28759657, 2017). "In addition, there is a review which focuses on the potential role of PPARγ in HIV-1-associated bone disease culminating with a provocative hypothesis stipulating a potential role for PPARγ in the reduced bone mass associated with HIV-1 infection and treatment." (PMID 19657396, 2009). "It cannot beexcluded that HIV-1 infection-mediated events affect PPARγ activity in adipose tissue through theseinteractions, although experimental evidence for this is lacking at present." (PMID 19081837, 2009). "The possibility that dysregulation of PPARγ (and the subsequent effect on both osteoblastogenesis and adipogenesis) is a contributory factor in the lipid- and bone-abnormalities observed in HIV-1 infection and treatment has also been investigated." (PMID 19325916, 2009). "The possibilitythat HIV-1 infection could influence PPARγ activity leads to the first consideration;whether the cells present in adipose tissue depots can be infected by HIV-1.The capacity of HIV-1 to infect adipocytes is controversial." (PMID 19081837, 2009). "Disturbances of PPARγ, as a master regulator of adipose tissuedifferentiation and function, may play a major role in the alterations ofadipose mass and lipid metabolism elicited by HIV-1 infection, and this issueis summarized in the present review." (PMID 19081837, 2009). "Recent research indicates that HIV-1 infection-related events may alter adipose tissue biology through several mechanisms involving PPARγ, ranging from direct effects of HIV-1-encoded proteins on adipocytes to the promotion of a proinflammatory environment that interferes with PPARγ actions." (PMID 19081837, 2009). "It must be taken into account that the action of HIV-1 infection in adipose tissue and PPARγ activity should not be considered only in relation to adipocytes." (PMID 19081837, 2009).
hyperandrogenism (5 papers, 2015 to 2024). Excessive secretion of androgens from the adrenal glands or gonads. "Why androgen excess has a different response on adipocytes in SAT versus VAT is unclear, though PPARγ may explain it in part." (PMID 35986388, 2022). "The network pharmacology analysis report found 988 PCOS-related genes, 108 hyperandrogenism-related genes, and 377 oligomenorrhea-related genes, and we finally shortlisted 5 common genes in PCOS, hyperandrogenism, and “oligomenorrhea”: NR3C1, PPARG, FOS, CYP17A1, and H6PD." (PMID 39294254, 2024).
invasive breast carcinoma (5 papers, 2008 to 2024). A carcinoma that infiltrates the breast parenchyma. "In 2005, an immunohistochemical test of 170 patients with invasive breast cancer showed that the expression of PPARγ was negatively associated with histological grade (p = 0.019)." (PMID 36611922, 2022). "PPARγ expression is inversely associated with histological grade in invasive breast carcinoma." (PMID 38516703, 2024). "In breast invasive carcinoma, particularly, PPARG and PPARGC1B were negatively correlated with tumor purity." (PMID 33029111, 2020). "Published NKI data from 294 young patients with primary invasive breast cancers was used to compare the expression of PPARγ and hTERT." (PMID 20650001, 2010).
kidney (5 papers, 2016 to 2025). "Moracin D was able to activate PPARγ/PKC-δand inhibit PKC-α, thereby inducing apoptosis in prostate cancerDU145 cells." (PMID 40392982, 2025). "Collectively, these results indicate that geniposide could significantly ameliorate acute kidney injury in CLP-induced septic mice and LPS-stimulated HK-2 cells by activating PPARγ." (PMID 33197894, 2020).
kidney stones (5 papers, 2016 to 2024). "The results showed that nephrolithiasis caused a significant downregulation of PPARG protein nuclear transcription factor activity in rat kidney tissue cells, and yellow tea administration significantly inhibited this effect." (PMID 37569334, 2023). "In conclusion, yellow tea may act as a potential PPARG agonist for the prevention and treatment of renal oxidative damage and fibrosis caused by kidney stones." (PMID 37569334, 2023). "Therefore, when kidney stones cause a decrease in PPARγ protein levels, its mRNA levels may increase compensatorily." (PMID 39325731, 2024). "Therefore, yellow tea may act as a potential PPARG agonist for prevention of renal oxidative damage and fibrosis caused by nephrolithiasis." (PMID 37569334, 2023). "There were two studies that both reported a decrease in PPARγ protein levels in the kidneys of rats with kidney stones." (PMID 39325731, 2024). "The results showed that yellow tea gavage significantly upregulated PPARG gene transcription levels in nephrolithiasis rats and showed a significant dose accumulation effect." (PMID 37569334, 2023). "Our findings revealed the role of flavonoids as PPARG agonists for the prevention and treatment of nephrolithiasis-related oxidative damage and fibrosis." (PMID 37569334, 2023). "How PPARA expression changes PPARG expression and activity in the nephrolithiasis inflammatory fibrosis process is still unclear." (PMID 37569334, 2023). "To clarify the roles of PPARα and PPARγ in kidney stone formation, we first examined their expression using hyperoxaluric stone model mice." (PMID 27022389, 2016). "Thus, our study not only discovered the role of imbalanced mitochondrial dynamics in kidney stone-related renal dysfunction but also further elucidated the intrinsic molecular mechanisms by which PPARγ agonist alleviates the progression of kidney stones." (PMID 39325731, 2024). "Our findings suggested that yellow tea could be a potential natural source of PPARG agonists for the prevention and treatment of nephrolithiasis." (PMID 37569334, 2023). "Our results showed that flavonoids in yellow tea could bind directly or indirectly to peroxisome proliferator-activated receptor gamma (PPARG) protein and affect kidney stone formation by regulating PPARG transcription factor activity." (PMID 37569334, 2023). "RT-qPCR analysis showed that H2O2 stimulation significantly reduced PPARG gene transcription in HK-2 cells, which is consistent with PPARG gene transcription and expression changes observed in the kidney tissue of nephrolithiasis rats (details are discussed in Section 2.5)." (PMID 37569334, 2023). "Although the exact role of PPARs in kidney stone pathogenesis is yet unknown, we revealed that PPARα and PPARγ exhibit differential effects on this process in hyperoxaluric mice and rats." (PMID 27022389, 2016). "Since PPARα and PPARγ are differentially expressed in the kidneys, it is reasonable that these two effectors play opposing roles in tubular cell CaOx crystal deposition and should be considered when treating MetS patients with kidney stones." (PMID 27022389, 2016). "We first confirmed PPAR expression changes including upregulation PPARG, TGF-β1, TNF-α, and MCP-1 expression in ethylene glycol-induced nephrolithiasis rats by RT-qPCR, immunofluorescence staining, and Western blot analyses." (PMID 37569334, 2023).
parasitemia (5 papers, 2010 to 2022). "PPARγ-mediated transcription of CD36, a scavenger receptor which enhances phagocytosis and facilitates the removal of parasitized erythrocytes, leads to reduced parasitemia." (PMID 22536211, 2012). "Whereas it is well known that many parasitic diseases are exacerbated by the activation of T helper 2, recent research on the anti-inflammatory alternatively activated macrophage (AAM), which is activated by PPARγ, shows that there is another facet to the host immune response." (PMID 22536211, 2012).
pituitary tumor (5 papers, 2011 to 2024). A benign or malignant neoplasm affecting the pituitary gland. "On the one hand, prolactin enhances PPARγ and C/EBPβ mRNA production and augments adipocytes differentiation in NIH-3T3 cells; on the other hand, TZDs activation of PPARγ inhibits prolactin function in pituitary tumor cells." (PMID 22135675, 2011). "Additionally, PPARα, PGC-1α, and FOXO1 ligands linked to acetylcarnitine may participate in the signaling pathways of prolactinoma, while SREBP-1c, LXRα/β, PPARγ, HIF-1α, PPARα, PGC-1α, and FOXO1 are likely involved in the signaling of nonfunctional pituitary tumors." (PMID 39669498, 2024).
sarcoma (5 papers, 2017 to 2024). A usually aggressive malignant neoplasm of the soft tissue or bone. "Then, we analyzed the expression of biomarkers of osteoblasts (COL1A1, BGLAP and RUNX2), chondrocytes (COL2A1, COMP and SOX9) and sarcoma (POSTN and DCN), adipocyte (LPL and PPARG) and BMSCs." (PMID 39715773, 2024). "T‐cells in the sarcoma microenvironment exhibited elevated levels of cytotoxicity (GZMB, GNLY and KLRD1), exhaustion (HAVCR2, CD38, CD160, CXCL13 and CX3CR1), and inflammation (IL33, PPARG, IL6R and SOCS3), suggesting an activated but exhausted phenotype." (PMID 39658531, 2024).
spinal cord injury (5 papers, 2008 to 2025). Penetrating and non-penetrating injuries to the spinal cord resulting from traumatic external forces (e.g., WOUNDS, GUNSHOT; WHIPLASH INJURIES; etc.). "This review will summarize thedocumented beneficial actions of PPARγ following CNS injury and illustrate how they may alsopromote anatomical and behavioral recovery after spinal cord injury (SCI)." (PMID 18401444, 2008). "The peroxisome proliferator-activated receptor gamma (PPAR-γ) agonist rosiglitazone inhibits NF-κB expression and endogenous neural stem cell differentiation into neurons and reduces the inflammatory cascade after spinal cord injury (SCI)." (PMID 30034460, 2018).
thyroid nodule (5 papers, 2012 to 2025). A small circumscribed mass in the THYROID GLAND that can be of neoplastic growth or non-neoplastic abnormality. "Furthermore, molecular analysis using the following markers (BRAF V600E, NRAS, HRAS, KRAS, RET/PTC, and PAX8/PPARg) to evaluate preoperative genetic mutations and rearrangements has been shown to have significant diagnostic value in thyroid nodules with indeterminate cytology." (PMID 37732121, 2023). "Recent large prospective studies have emphasized the ability of genetic markers (BRAF, RAS, RET/PTC, and PAX8/PPARγ) and protein markers (galectin-3) to significantly improve and affect the preoperative diagnostic accuracy especially for patients who have indeterminate thyroid nodules." (PMID 23326756, 2012). "Therefore, the targets widely recognized and recommended by scholars at home and abroad were selected to compose a 6-gene test panel for thyroid nodule diagnosis, including BRAF V600E mutation, TERT mutation, and gene fusions (CCDC6-RET, NCOA4-RET, ETV6-NTRK3, EML4-NTRK3, STRN-ALK, and PAX8/PPARG)." (PMID 40586006, 2025).
brain edema (4 papers, 2018 to 2022). Increased intracellular or extracellular fluid in brain tissue. "An important observation from our results is the overall higher expression of these transcriptional regulators, namely PPARG, REL, and NFE2L2 in PBMC at a delayed time point (>72 h), which falls within the time point of progressive cerebral edema after ICH." (PMID 33564466, 2021).
celiac disease (4 papers, 2016 to 2024). An autoimmune genetic disorder with an unknown pattern of inheritance that primarily affects the digestive tract. "It has also been shown that tTGA drives inflammation via PPARG down-regulation in celiac patients and that down-regulation of proteins involved in PPAR signaling are associated with the highest celiac disease histological score." (PMID 27483138, 2016). "Another finding from this study was the down-regulation of mRNA levels of both PPARA and PPARG in celiac disease children as compared with controls." (PMID 27483138, 2016).